DHODH (dihydroorotate dehydrogenase (quinone))
Diseases named in the same sentence as DHODH in open-access papers (continued):
Sharing a sentence is not in itself a finding about the gene and the disease.
glioma (8 papers, 2020 to 2025). A benign or malignant brain and spinal cord tumor that arises from glial cells (astrocytes, oligodendrocytes, ependymal cells). "Indeed, mutant IDH activity sensitizes glioma cells to DHODH inhibition by increasing their susceptibility to replication‐dependent DNA damage caused by nucleotide pool imbalances." (PMID 38105543, 2025). "Additionally, BAY2402234 functions as a DHODH inhibitor and has been used to treat gliomas by causing sustained DNA damage." (PMID 40442064, 2025). "More recently, several brain tumor types including IDH-mutant gliomas have been found to be sensitive to inhibitors of dihydroorotate dehydrogenase (DHODH), an enzyme in the de novo pyrimidine synthesis pathway." (PMID 39025958, 2024). "The IDH‐mutant gliomas are particularly dependent on the de novo pyrimidine biosynthesis, since inhibitors targeting enzymes of this metabolism including DHODH, preferentially kill IDH1‐mutant glioma cells and patient‐derived IDH‐mutant GSC compared to IDH‐wild type cells." (PMID 38105543, 2025). "More recently, the dihydroorotate dehydrogenase (DHODH) inhibitor BAY2402234 showed blood–brain barrier penetration and promising efficacy in IDH mutant glioma, diffuse midline glioma, and MYC-amplified medulloblastoma." (PMID 39195509, 2024). "Intriguingly, high expression of DHODH, a rate-limiting step in de novo pyrimidine synthesis, was adversely prognostic in patients with IDH mutant GBM, which suggests that further investigation of pyrimidine biosynthesis could be interesting in gliomas with an IDH mutation." (PMID 32732914, 2020). "A brain penetrant DHODH inhibitor, BAY2402234, was tested in both glioma models." (PMID 38105543, 2025). "The specific inhibition on DHODH, the key enzyme of pyrimidine synthesis, could have a very good effect on the treatment of patients with IDH1 mutant glioma." (PMID 36568190, 2022). "GPX4, FSP1, and GCH1 were highly expressed, while DHODH expression was low in patients with gliomas with a 1p19q non-codeletion compared to those with a 1p19q codeletion." (PMID 35174170, 2021). "The analysis of mRNA expression profiles of glioma samples and non-tumor brain tissues provided evidence that GPX4, FSP1, and DHODH were highly expressed in tumoral tissue compared to that in non-tumor brain tissues." (PMID 35174170, 2021). "Our analysis showed that GPX4, FSP1, GCH1, and DHODH were more highly expressed in tumor tissue than in non-tumor brain tissue, especially in high-grade, IDH1 wild type, 1p19q non-codeletion gliomas, suggesting that glioma cells had a strong potential to resist ferroptosis." (PMID 35174170, 2021).
malaria (8 papers, 2015 to 2025). Malaria is a serious and sometimes fatal disease caused by a parasite that commonly infects a certain type of mosquito which feeds on humans. "Previous work found that, in some cases, malaria parasites that evolved resistance to one type of DHODH inhibitor (by acquiring mutations in their DHODH enzyme) then became more vulnerable to another kind." (PMID 37737220, 2023). "Several new malaria drugs being explored in preclinical research work by binding to an enzyme known as DHODH and preventing it from performing its usual role in the parasite." (PMID 37737220, 2023). "DSM265, a triazolo-pyrimidine-based inhibitor of DHODH developed by Philips, is the first DHODH inhibitor able to reach clinical research for the treatment of malaria." (PMID 33971967, 2021). "De novo pyrimidine biosynthesis is known to be indispensable for Toxoplasma gondii and for more than a decade, the fourth enzyme in the pathway, DHODH, has been studied as a drug target to control malaria." (PMID 31316493, 2019). "In malaria parasite, Plasmodium falciparum, DHODH has been recognized as a latent drug target to inhibit malarial activity in vivo." (PMID 30200251, 2018). "Here we present our winning interactive pharmacophore modeling virtual screening workflow for targeting the anti-malaria dihydroorotate dehydrogenase (DHODH) enzyme and report the results of the follow-on experimental validation from the 2012 TDT competition." (PMID 26258606, 2015). "DHODH inhibitors are also found to be effective against oomycete phytophthora infestans, schistosomiasis, invasive fungal infections, eumycetoma, and malaria." (PMID 33971967, 2021). "Therefore, DHODH is a high-potential drug target, for example leflunomide, a DHODH specific inhibitor, is used to treat malaria and Pneumocystis jiroveci infections as a low molecular weight compound." (PMID 30200251, 2018). "Together, these findings suggest that the DHODH enzyme may not be the best target for new malaria drugs because many it can acquire many possible mutations that confer resistance." (PMID 37737220, 2023). "More recently, other de novo purine and pyrimidine synthesis inhibitors have been developed, such as dihydroorotate dehydrogenase (DHODH) inhibitors for cancer treatment and plasmodial SHMT inhibitors for malaria treatment." (PMID 34341479, 2022).
lymphoma (7 papers, 2021 to 2026). A malignant (clonal) proliferation of B- lymphocytes or T- lymphocytes which involves the lymph nodes, bone marrow and/or extranodal sites. "Several DHODH inhibitors are clinically advanced: AG-636 shows antitumor activity in lymphoma models (10–100 mg/kg BID, 14 days) and has entered Phase 1 testing (NCT03834584)." (PMID 41549155, 2026). "The results indicated that lymphoma cells depended on DHODH for intracellular uridine synthesis and could survive on the salvage pathway, including uridine uptake from the environment." (PMID 38918775, 2024). "Vidofludimus is a DHODH inhibitor with potential anti-inflammatory, immunomodulating, and anti-viral activities, recently shown to promote cell cycle arrest in lymphoblastoid and lymphoma cell lines." (PMID 36835644, 2023). "DHODH inhibition prevents EBV lymphomas in a humanized mouse model." (PMID 34281398, 2021). "Furthermore, the de novo pyrimidine synthesis enzyme DHODH inhibitor leflunomide impairs growth of EBV-driven lymphomas in murine models." (PMID 34281398, 2021). "To develop and assess new therapeutics, we investigated the effects of the DHODH inhibitor brequinar and the synthetic effects of brequinar and venetoclax in the HGBCL lymphoma cell lines and xenograft mice model." (PMID 38918775, 2024).
cervical cancer (5 papers, 2021 to 2025). A primary or metastatic malignant neoplasm involving the cervix. "Combined DHODH inhibition and cisplatin synergistically enhance ferroptosis by downregulating the mTOR pathway, offering a potential therapeutic strategy for cervical cancer." (PMID 40895556, 2025). "Downregulation of DHODH has been shown to induce ferroptosis and suppress the proliferation of cervical cancer cells, while DHODH inhibition-mediated ferroptosis induction has been reported to strengthen the radiosensitivity of nasopharyngeal carcinoma cells." (PMID 40917841, 2025). "DHODH is upregulated in cervical cancer and acts as a ferroptosis defender; its inhibition promotes ferroptosis and suppresses tumor cell proliferation." (PMID 40895556, 2025). "Given that DHODH inhibition repressed cervical cancer cells’ proliferation by cell death promotion, the role of DHODH inhibition in inducing ferroptosis was investigated." (PMID 36672495, 2023). "Surprisingly, the combination of cisplatin and DHODH inhibition significantly downregulated the mTOR pathway activity in our study, which is critically involved in inducing ferroptosis in cervical cancer cells." (PMID 36672495, 2023). "This study proposed that the combination of DHODH inhibition and cisplatin offers a potential treatment for cervical cancer." (PMID 36672495, 2023). "Cervical cancer cells were suppressed in proliferation and induced death after DHODH knockdown or brequinar treatment." (PMID 36672495, 2023). "The current study demonstrated that DHODH inhibition suppressed the growth and promoted cell death in cervical cancer via ferroptosis." (PMID 36672495, 2023). "Initially, we compared the expression of DHODH protein expression in tissues of cervical cancer with adjacent normal tissues using an IHC assay." (PMID 36672495, 2023). "Each CI with different drug concentrations in both CaSki and HeLa cells was less than 1, demonstrating that DHODH inhibition exerted a synergistic anticancer function with cisplatin in cervical cancer cells." (PMID 36672495, 2023). "Collectively, it appears that DHODH inhibition promotes cervical cancer cell death by inducing ferroptosis." (PMID 36672495, 2023). "Then, the DHODH-silenced cell lines were generated and analyzed for ferroptosis in cervical cancer cells." (PMID 36672495, 2023). "This study demonstrates that DHODH inhibition inhibits cervical cancer cells’ cell proliferation and induces cell death through ferroptosis." (PMID 36672495, 2023). "Our work proposes that the combination of DHODH inhibition and cisplatin is a potential strategy for cervical cancer treatment." (PMID 36672495, 2023). "Silence of DHODH or pharmacologic inhibition promoted the ferroptotic death in cervical cancer cells." (PMID 36672495, 2023). "In vitro, either genetic knockdown or pharmacological inhibition of DHODH suppresses the proliferation of cervical cancer cells." (PMID 36672495, 2023). "Herein, using an immunohistochemistry (IHC) staining assay, we detected the DHODH expression in tissues of cervical cancer." (PMID 36672495, 2023). "In parallel to DHODH silence, brequinar, a specific inhibitor of DHODH, was used to suppress the DHODH activity in cervical cancer cells." (PMID 36672495, 2023). "Further, an fluorescence detection assay for measuring DHODH activity is developed in cultured HeLa cervical cancer cells, and in stage III stomach cancer and adjacent normal tissues from the same patient." (PMID 33971967, 2021). "Furthermore, DHODH inhibition enhanced cervical cancer cell sensitivity to cisplatin through inducing ferroptosis in vitro and in vivo." (PMID 36672495, 2023). "Based on the ferroptotic role of DHODH inhibition, whether DHODH inhibition could sensitize cervical cancer cells to cisplatin through inducing ferroptosis was further explored." (PMID 36672495, 2023).
cervical cancer (continued). "In conclusion, the occurrence of significant ferroptosis in cervical cancer cells may be mediated via suppression of mTOR pathway after DHODH inhibition and cisplatin combination treatment." (PMID 36672495, 2023). "However, the role of DHODH inhibition in cervical cancer cells is unclear, particularly in synergy with cisplatin via ferroptosis." (PMID 36672495, 2023). "A high level of DHODH was detected in cervical cancer tissues here." (PMID 36672495, 2023). "In conclusion, DHODH was upregulated in cervical cancer tissues." (PMID 36672495, 2023). "DHODH inhibition inhibited the proliferation and promoted the ferroptosis in cervical cancer cells." (PMID 36672495, 2023). "The expression of DHODH was increased in cervical cancer tissues." (PMID 36672495, 2023). "Moreover, the combination of DHODH inhibition and cisplatin synergistically inhibits the growth of cervical cancer cells in vitro and in vivo by ferroptosis via the mTOR pathway." (PMID 36672495, 2023). "Moreover, inhibiting DHODH in cervical cancer cells both in vitro and in vivo produced a synergistic anticancer effect with cisplatin, which may be achieved by mTOR pathway suppression." (PMID 36672495, 2023). "Therefore, the combination of DHODH inhibition and cisplatin exhibits synergistic effects on ferroptosis induction via inhibiting the mTOR pathway could provide a promising way for cervical cancer therapy." (PMID 36672495, 2023). "A significant increase in DHODH expression was observed in cervical cancer tissues but not in normal tissues." (PMID 36672495, 2023).
hepatocellular carcinoma (5 papers, 2023 to 2025). A malignant tumor that arises from hepatocytes. "In hepatocellular carcinoma, low GPX4 expression amplifies susceptibility to DHODH blockade, leading to robust ferroptotic responses and enhanced therapeutic efficacy." (PMID 41369379, 2025). "In hepatocellular carcinoma, the YBX1–RNF115 regulatory circuit promotes DHODH stability through ubiquitination control, further suppressing ferroptosis and supporting tumor growth." (PMID 41369379, 2025). "Research has also shown that targeting exosomes from DHODH and GPX4 enhances sorafenib-induced ferritic anaemia, thereby increasing the sensitivity of hepatocellular carcinoma (HCC) cells to sorafenib." (PMID 38509409, 2024). "To validate FSP1 as a central target of ginsenoside RK1-mediated ferroptosis in hepatocellular carcinoma, we engineered overexpression plasmids for GCH1, DHODH, GPX4, and FSP1, respectively, and transfected them into HepG2 cells." (PMID 39065721, 2024). "Remarkably, while overexpression of GCH1, DHODH, and GPX4 failed to significantly increase cell viability in hepatocellular carcinoma cells, overexpression of FSP1 led to a substantial increase in cell viability." (PMID 39065721, 2024). "Notably, overexpression of GCH1, DHODH, and GPX4 did not mitigate the heightened ferroptosis sensitivity induced by ginsenoside RK1 in hepatocellular carcinoma cells." (PMID 39065721, 2024).
liver cancer (5 papers, 2018 to 2025). An epithelial or non-epithelial malignant neoplasm that arises from the liver. "Intriguingly, CAD is also associated with unfavorable survival in liver cancer and renal cancer, and it catalyzes the rate-limiting step of the de novo PS pathway, suggesting it may be expressed at higher levels than DHODH and UMPS in de novo PS to ameliorate chemotherapy induced genotoxic damage." (PMID 30038717, 2018). "Compared with that in normal tissues, DHODH was significantly upregulated in paired and unpaired tissues of various tumors, including liver cancer, ccRCC, and cholangiocarcinoma (except for MESO), aligning with the results from the TIMER database." (PMID 38796629, 2024). "In terms of drug resistance, further studies have revealed that LOXL3 promotes chemoresistance in liver cancer by stabilizing dihydroorotate dehydrogenase (DHODH) through activation of the intramitochondrial adenylate kinase 2 (AK2)-LOXL3-DHODH pathway, thereby inhibiting mitochondrial ferroptosis." (PMID 41250755, 2025). "Moreover, the lysyl-oxidase (LOX) family protein LOXL3 attenuates the ubiquitination of DHODH, in turn inducing the accumulation of DHODH proteins in liver cancer." (PMID 40715045, 2025).
medulloblastoma (5 papers, 2023 to 2025). A malignant, invasive embryonal neoplasm arising from the cerebellum. "In aggressive group 3 medulloblastoma, a childhood brain tumour, DHODH activity is linked to the MYC gene, which drives tumour growth." (PMID 39766063, 2024). "A most recent study reveals that the activity of the mTOR pathway is strongly attenuated in DHODH-knockout medulloblastoma SU_MB002 cell lines, thereby inducing cell-cycle arrest and apoptosis." (PMID 36672495, 2023).
multiple myeloma (5 papers, 2017 to 2023). "Here, the aim of the study was to assess the role of DHODH in the cytotoxicity of leflunomide in relation to the multiple myeloma cell line RPMI 8226." (PMID 34577124, 2021). "Cell cycle analysis results also indicate the DHODH- independent toxicity of teriflunomide in multiple myeloma cell line." (PMID 34577124, 2021).
pancreatic cancer (5 papers, 2021 to 2025). "DHODH inhibitors have been shown to induce ferroptosis in cancer cells and to exert antitumor effects in pancreatic cancer models." (PMID 41243973, 2025). "Pharmacological inhibition of DHODH, which blocks de novo pyrimidine synthesis, similarly decreased tumor burden with enhanced phagocytosis in pancreatic cancer models." (PMID 41243973, 2025). "DHODH reveals higher mRNA level in human pancreatic cancer tissues compared with normal pancreatic tissue." (PMID 33971967, 2021). "Gemcitabine, a first-line choice for pancreatic cancer, is an ideal combination partner for DHODH inhibitors." (PMID 33971967, 2021). "However, in pancreatic cancer it is unclear how DHODH inhibition can regulate apoptosis sensitivity." (PMID 40738904, 2025). "Consistently, we observed an increase of phagocytic macrophages in BAY2402234 treatment group compared with vehicle group, indicating that pharmacological inhibition of DHODH could inhibit tumor growth and potentiate phagocytosis in pancreatic cancer model." (PMID 41243973, 2025). "Pharmacologic inhibition of dihydroorotate dehydrogenase (DHODH), an enzyme in the de novo pyrimidine synthesis pathway, delays pancreatic tumor growth; however, limited monotherapy efficacy suggests that compensatory pathways may drive resistance." (PMID 40738904, 2025). "As gemcitabine treatment leads to increased de novo pyrimidine synthesis in pancreatic cancer cells, combination of DHODH inhibitor Ter with gemcitabine reversed gemcitabine-induced nucleoside synthesis and thus exhibits synergistic effect against pancreatic cancer proliferation." (PMID 33971967, 2021). "Ultimately, this suggests that mitochondrial fusion may work in tandem with DHODH inhibition as a tumor suppressive mechanism in pancreatic cancer." (PMID 34564443, 2021). "Notably, DHODH inhibition induces cell cycle S phase arrest and mitochondrial depolarization in KP-4 human pancreatic cancer cells." (PMID 33971967, 2021). "It manifests that DHODH may play a vital role in pancreatic cancer and its depletion might contribute to anti-cancer efficiency." (PMID 33971967, 2021). "Collectively, DHODH inhibitor may provide a novel way for pancreatic cancer treatment." (PMID 33971967, 2021). "Here we demonstrate for the first time that Lef inhibits DHODH as measured by upstream metabolite accumulation both in vitro and in vivo in a KPC syngeneic immunocompetent model of pancreatic cancer." (PMID 34239352, 2021).
acrofacial dysostosis (4 papers, 2017 to 2024). "Miller syndrome, a skeletal dysplasia also known as postaxial acrofacial dysostosis, is caused by biallelic pathogenic variants in human DHODH and became the first Mendelian disorder whose molecular basis was revealed by whole-exome sequencing." (PMID 39430512, 2024).
colorectal cancer (4 papers, 2019 to 2026). A primary or metastatic malignant neoplasm that affects the colon or rectum. "For example, in colorectal cancer, redistribution of DHODH from mitochondria to the cytosol was shown to drive 5-fluorouracil (5-FU) resistance by sustaining pyrimidine synthesis independently of mitochondrial metabolism, thereby dampening drug efficacy." (PMID 41369379, 2025). "In gastric and colorectal cancers, DHODH upregulation confers resistance to 5-FU and platinum-based chemotherapy by enhancing glycolytic flux and pyrimidine synthesis." (PMID 41369379, 2025). "Targeting DHODH and disruption of the pyrimidine biosynthesis are demonstrated to be an approach to small cell lung cancer and colorectal cancer therapy." (PMID 33060568, 2020). "Consistent with this, metastasizing colorectal cancer cells generated more nucleotide precursors, and inhibiting the enzyme involved in nucleotide synthesis (DHODH) with an arthritis drug called leflunomide stopped colorectal cancer cells from spreading." (PMID 31841108, 2019).